FOXO1 (forkhead box O1)
Diseases named in the same sentence as FOXO1 in open-access papers (continued):
Sharing a sentence is not in itself a finding about the gene and the disease.
gastric cancer (continued). "In vitro analyses with Western blotting and semiquantitative reverse transcription-polymerase chain reaction were performed using the stable SNU-638 gastric cancer cell line transfected with lentivirus-delivered FOXO1 short hairpin RNA." (PMID 21696576, 2011). "The present study was performed to investigate the correlation between the constitutive expression of phosphorylated FOXO1 (pFOXO1) and angiogenesis in gastric cancer." (PMID 21696576, 2011). "Previously, it was reported that the phosphorylated inactive form of FOXO1 (pFOXO1) was constitutively expressed in gastric cancer and that this was clinically significant." (PMID 21696576, 2011). "Additionally, CircMRPS35 increases the acetylation of H4K5 in the promoter region of FOXO1 and FOXO3a by recruiting KAT7, thereby upregulating the upregulation of FOXO1 and FOXO3a, and finally inhibiting the proliferation and invasion of gastric cancer cells." (PMID 38505423, 2024). "Upon exposure to cisplatin, FOXO1 was activated in gastric cancer cells." (PMID 38125769, 2023). "To further investigate whether SIRT1 affects the malignant biological behavior of gastric cancer cells under GD conditions through FoxO1-Rab7-autophagy, we used siRNA interference technology to artificially reduce the expression of FoxO1 or Rab7 in cells." (PMID 37293593, 2023). "In addition, circMRPS35 located in the nucleus can recruit and bind with histone acetyltransferase KAT7 to induce histone acetylation of FoxO1/3a promoter region, which dramatically activated transcription of FOXO1/3a in gastric cancer progression." (PMID 36139074, 2022). "Similarly, upregulated LINE derived-miR-552 also functions as an oncogenic miRNA, as an accelerator of gastric cancer progression, increased metastasis, and worsens therapeutic outcomes by targeting forkhead box O1 (FOXO1) and modulating the PI3K/AKT pathway." (PMID 36142830, 2022). "Notably, phosphorylation of FOXO1 blocks the proliferation and angiogenesis of gastric cancer cells, improves the overall survival rate of patients with gastric cancer, and decreases tumor metastasis rates." (PMID 34123834, 2021). "Upregulated miR-132 in gastric cancer inhibits the translation process by binding to the 3'-untranslated region (3' -UTR) of Forkhead box O class protein 1 (FoxO1) messenger RNA (mRNA) to inhibit the inhibitory effect of FoxO1 on cells and promote the development of gastric cancer." (PMID 34659567, 2021). "Also, the anti-angiogenic role of FOXO1 has been documented in gastric cancer, which when inhibited contributes to tumor growth by upregulating HIF-1α and VEGF." (PMID 32364530, 2020). "Using both in vitro and in vivo studies, they found that the miR-135b transported in exosomes derived from another gastric cancer cell line (SGC7-901) inhibited the FOXO1 expression in HUVEC cells and enhanced the growth of blood vessels, promoting angiogenesis." (PMID 33233600, 2020). "Promotes angiogenesis in gastric cancer via downregulation of forkhead box O1 (FOXO1)." (PMID 33363174, 2020). "Moreover, circMRPS35 expression positively correlates with that of FOXO1/3a in gastric cancer tissues." (PMID 32164722, 2020). "Albeit, this would depend on whether the G9a-FOXO1 interaction identified in colon cancer holds true in the context of FOXO1-inhibition of angiogenesis in gastric cancer." (PMID 33088284, 2020). "Either FOXO1 or FOXO3a expression was significantly decreased in gastric cancer tissues." (PMID 32164722, 2020). "In conclusion, our study demonstrates that circMRPS35 recruits histone acetyltransferase KAT7 as a modular scaffold, which subsequently increases the level of H4K5ac in the promoter regions of FOXO1 and FOXO3a and ultimately suppresses the proliferation and invasion of gastric cancer cells." (PMID 32164722, 2020). "Moreover, Park J et. al. verified that FOXO1 is involved in drug resistance via the phosphoinositide 3-kinase/Akt pathway in gastric cancer." (PMID 31400752, 2019).
gastric cancer (continued). "It has been reported that FOXO1 induced PI3K/AKT signaling in gastric cancer." (PMID 30618730, 2018). "Similarly, FOXO1 inactivation was previously shown to be an early event and was positively correlated with better prognosis in gastric cancer." (PMID 27268017, 2016). "In order to investigate whether JNK-induced colony formation is mediated by FOXO1 inactivation in gastric cancer cells, we used a combination of JNK inhibition and FOXO1 knockdown." (PMID 27268017, 2016). "Since the biological function of c-Jun N-terminal kinase (JNK) in gastric cancer remains unclear, we investigated the clinical significance of JNK activation and its association with FOXO1 activation." (PMID 27268017, 2016). "Western blotting showed that SP600125 treatment of gastric cancer cells with a various concentrations resulted in a substantial decrease in the protein expression of the inactive form of FOXO1 (pFOXO1) in a dose dependent manner, whereas the protein expression of total FOXO1 was not changed." (PMID 27268017, 2016). "Animal experiments are needed to confirm the anti-angiogenic role of FOXO1 in human gastric cancer." (PMID 21696576, 2011). "In addition, we performed cell culture experiments after establishing a stable gastric cancer cell line transfected with lentivirus-delivered FOXO1 short hairpin RNA (shRNA)." (PMID 21696576, 2011). "Likewise, FOXO1 plays similarly paradoxical roles in different gastric cancer research settings." (PMID 36290822, 2022). "In summary, the antitumor effect of gramicidin on gastric cancer cells was preliminarily explored, in which gramicidin may inhibit cell proliferation and induce G2/M cell cycle block by down-regulating the FoxO1 and cyclinD1 while down-regulating tumor suppressor genes Bcl-2 to induce apoptosis." (PMID 31767027, 2019). "Furthermore, we found that JNK negatively regulates FOXO1 activation in gastric cancer cells." (PMID 27268017, 2016). "Thus, JNK/FOXO1 pathway seems to contribute to tumor growth of gastric cancer." (PMID 27268017, 2016). "In our study, we found that ET-1 was low-expressed in EBV-positive gastric cancer cells, which was due to the inhibition of ERK signaling by EBNA1 through the repression of FOXO1 expression." (PMID 36475746, 2023). "In view of the consistent expression of p-ERK, FOXO1, and ET-1 in gastric cancer cell lines and tissues, it is believed that EBV can regulate the expression of ET-1 via the MAPK/ERK/FOXO1 pathway." (PMID 36475746, 2023). "Upregulated miR-132-3p promotes gastric cancer (AGS) cell growth by binding to the 3′-UTR of FOXO1 mRNA and, consequently, blocking FOXO1 function." (PMID 36835100, 2023). "In gastric cancer, USP22 stabilizes the c-Myc/nicotinamide phosphoribosyltransferase (NAMPT)/SIRT1 signaling cascade, which further activates forkhead box protein O1 (FOXO1) and YAP." (PMID 33919439, 2021). "USP22 also promoted gastric cancer progression and metastasis through regulating c-Myc/NAMPT/SIRT1-dependent FOXO1 and YAP signaling." (PMID 34753387, 2021). "miR-107 acts as an oncogene and regulates gastric cancer development and progression by targeting NF1, DICER1, FOXO1, and CDK825,27,28,41." (PMID 30258124, 2018). "Since gastric cancer specimens showed a positive correlation between JNK activation and FOXO1 inactivation in the present study, the combined status of JNK activation and FOXO1 inactivation was assessed in relation to survival." (PMID 27268017, 2016). "JNK inhibition in SNU-638 cells increased FOXO1 activation and suppressed the nuclear export of FOXO1, which suggested that FOXO1 is a nuclear substrate of JNK in gastric cancer cells." (PMID 27268017, 2016). "Data from miRNA target prediction databases and a literature search identified numerous tumor suppressive targets of the oncogenic miR-9, including FOXO1 in both non-small cell lung cancer and endometrial cancer and CDX2 in gastric cancer." (PMID 27612152, 2016).
gastric cancer (continued). "We found that cytoplasmic pFOXO1 expression in gastric cancer cells was positively correlated with MVA (P = 0.048), suggesting that FOXO1 is involved in gastric tumor angiogenesis." (PMID 21696576, 2011). "Moreover, ITGA2 silencing induces apoptosis in gastric cancer and is able to restore sensitivity to paclitaxel in ovarian cancer via inhibition of AKT/FOXO1 signaling." (PMID 36765586, 2023). "In gastric cancer (GC), SIRT1 silencing or inhibiting its activity by EX527 enhances expression of FOXO1, pro-apoptotic BAX, and E-cadherin, whereas the expression of Ki67, Cyclin D1, anti-apoptotic Bcl-2, Vimentin, MMP-2 and MMP-9 are downregulated, suggesting SIRT1 involvement in GC progression." (PMID 34769241, 2021). "In vitro FOXO1 silencing enhances the upregulation of HIF-1α and gastric cancer cell growth." (PMID 32629884, 2020). "Resveratrol, which has been shown to induce autophagy-mediated cell death in leukemia and gastric cancer cells, showed autophagy inhibition in CCA by promoting deacetylation of FOXO1, impairing FOXO1 binding to Atg7 and blocking autophagy initiation in CCA cells, finally leading to apoptosis." (PMID 32143356, 2020). "Taken together, our data indicate that JNK acts as an inhibitory upstream molecule of FOXO1 in the FOXO1 pathway in gastric cancer cells, and that crosstalk between these molecules does not exist." (PMID 27268017, 2016). "Since JNK activation increased gastric cancer cell growth through inhibition of FOXO1, combination of targeting JNK/FOXO1 pathway may further reduce gastric cancer cell growth." (PMID 27268017, 2016). "Additionally, we found that colony formation of gastric cancer cells was decreased by pharmacological inhibition of JNK, whereas it was increased by FOXO1 shRNA transfection." (PMID 27268017, 2016). "In addition, FOXO1 staining in gastric cancer was not an independent prognostic factor." (PMID 27268017, 2016).
ovarian carcinoma (60 papers, 2008 to 2026). A malignant neoplasm originating from the surface ovarian epithelium. "The present study was designed to determine the pattern of the expressions of miR-340, LGR5, and FOXO1 genes in ovarian cancer tissue samples as well as their association with drug resistance in ovarian cancer cell lines." (PMID 33718760, 2021). "Reduced expression of FoxO1 has been associated with resistance to conventional agents (e.g., cisplatin) and with reduced efficacy of drug combinations in ovarian carcinoma cells." (PMID 30646603, 2019). "FOXO1 plays a critical role in diverse cancer-related processes, including cellular differentiation, apoptosis, cell cycle arrest, and the response to DNA damage, and is associated with poor prognosis in epithelial ovarian cancer patients." (PMID 38612604, 2024). "Since FOXO1 is linked to cytotoxic stress induced by paclitaxel and contributes to drug-resistance in ovarian cancers, we supposed that ITGA2 might play an important biological role in drug-resistance in ovarian tumors." (PMID 32202508, 2020). "Correlation appears to be negative between the expression of Mirk protein and the total level of FoxO (FoxO1+FoxO3A) in ovarian cancer cells (R2=0.946 and P<0.001), suggesting FoxO1 and/or FoxO3A may be associated with Mirk function or kinase activity." (PMID 22159921, 2012). "In addition,FOXO1 is a cisplatin sensitivity gene in cell lines andMSN, was identified as a novel diagnostic marker fordistinguishing ovarian cancer from colon cancer." (PMID 21423607, 2011). "Silencing of RUNX1 reduced EMT and increased apoptosis via the FOXO1-Bcl2 axis while MICAL2 silencing suppressed ovarian cancer proliferation and migration, promoting a MET." (PMID 41282576, 2026). "Propofol inhibits the resistance of ovarian cancer cells to cisplatin by regulating the miR-374a/FOXO1 signaling pathway, which provides more favorable evidence for propofol in the anesthesia of ovarian cancer patients." (PMID 40309242, 2025). "In breast and ovarian cancer cells, the phosphorylation of FOXO1 by DYRK1B resulted in decreasing transcriptional activity." (PMID 37120440, 2023). "Interesting, it has not been reported that the specific mechanism by which RUNX1 regulates ovarian cancer cell apoptosis through FOXO1." (PMID 38057816, 2023). "RUNX1 knockdown inhibits the physiological function of ovarian cancer cells and regulates apoptosis through the FOXO1-Bcl2 axis." (PMID 38057816, 2023). "In paclitaxel-resistant ovarian cancer cells, Trx1 is involved in overcoming drug toxicity by binding to the FOXO1 transcription factor, inducing its nuclear translocation, and enhancing FOXO1 transcriptional activity." (PMID 35664671, 2022). "The signaling axis of miR-374a/FOXO1 was first verified in ovarian cancer, and miR-374a was found to modulate FOXO1 to control the proliferation in ovarian cancer cells." (PMID 36359865, 2022). "Several study provides information regarding downregulated FOXO1 protein level in cancers, including glioblastoma, endometrial, ovarian carcinoma, prostate, and lung carcinoma." (PMID 36539739, 2022). "Compare to the paired adjacent normal tissues, a significant increase in the expression of the LGR5 gene and a significant decrease in expression of the miR-340 and FOXO1 genes were observed in the tissue samples of the patients with ovarian cancer." (PMID 33718760, 2021). "For example, FOXO1 is overexpressed in paclitaxel-resistant ovarian cancer cells, which can protect these ovarian cancer cells from oxidative stress-induced apoptosis through regulation of superoxide dismutase 2 (SOD2)." (PMID 34123834, 2021). "In ovarian cancer, the progesterone receptor (PR‐B) induces cell senescence through FOXO1, and one of the characteristics of aging cells is the upregulation of FOXO1 expression." (PMID 34825509, 2021). "Disturbance in the expression of the FOXO1 gene can also affect the drug resistance induction in a number of cancers, including ovarian cancer." (PMID 33718760, 2021).
ovarian carcinoma (continued). "Gao and colleagues reported that FOXO1 contributes to Mirk-mediated cell survival and ovarian cancer chemosensitivity to cisplatin." (PMID 32948132, 2020). "A previous study has considered the forkhead transcription factor FOXO1 as a transcriptional factor, which can develop drug resistance in ovarian cancer." (PMID 32660222, 2020). "Recently, FoxO1 has been shown to induce cellular senescence in ovarian cancer cells by the co-recruitment with progesterone receptor to the p21 promoter region." (PMID 32398756, 2020). "Curcumin exerts its cytotoxic effects against SKOV3 ovarian cancer cells largely through the upregulation of miR-9 and the subsequent modulation of the Akt/FOXO1 axis." (PMID 31480018, 2019). "In ovarian carcinoma cell models resistant to cisplatin, a down-regulation of FoxO1 levels has been reported following whole genome expression analysis." (PMID 30646603, 2019). "Trx 1 promoted paclitaxel-induced drug resistance by increasing FOXO1 transcriptional activity and suppressing drug-induced apoptosis in ovarian cancer A2780 cell." (PMID 31470801, 2019). "An impairment of the ability of cisplatin to activate FoxO signaling has been reported both for FoxO1 in ovarian carcinoma cells and FoxO3 in colon cancer cells." (PMID 30646603, 2019). "In ovarian carcinoma cells resistant to the microtubule stabilizer paclitaxel, increased levels of FOXO1 and the small redox protein thioredoxin (Trx1) have been described." (PMID 30646603, 2019). "In a novel study, the mRNA expression level of miR-27a, which activates the Wnt/β-catenin signaling pathway through the inhibition of FOXO1, was significantly higher in ovarian cancer tissues and in in vitro ovarian cancer cell lines." (PMID 31572683, 2019). "Cytoplasmic Foxo1 has been shown to be particularly high expression both in paclitaxel-resistant ovarian cancer cell lines and clinical samples." (PMID 26055813, 2015). "Cytoplasmic FOXO1 overexpression was frequently observed in ovarian cancer tissue samples from chemoresistant patients compared to chemosensitive patients." (PMID 23874926, 2013). "Our previous studies have also shown Mirk/Dyrk1B function in an NSCLC orthotopic mouse model, and the involvement of FoxO1/3A in the Mirk-mediated ovarian cancer cell survival." (PMID 23311607, 2013). "Mirk/Dyrk1B-mediated cell survival and chemosensitivity is correlated with expression and nuclear translocation of FoxO1 and/or FoxO3A in ovarian cancer." (PMID 22159921, 2012). "In this study, we showed that Mirk/Dyrk1B protein was overexpressed in 5 of 8 ovarian cancer cell lines and negatively correlated with the protein level of FoxO factors (FoxO1+FoxO3A)." (PMID 22159921, 2012). "To determine further the relevance of FOXO1 target genes in ovarian cancer cells, we also compared the levels of p27Kip1, MnSOD, catalase and GADD45α expression in KF28, KFr13 and KFr13Tx cells by western blotting." (PMID 18319717, 2008). "In ovarian cancer cell lines, FOXO1 expression and its correlation with paclitaxel treatment was investigated by cytotoxic assay and silencing experiment." (PMID 18319717, 2008). "Additionally, FOXO1 influences ovarian cancer cell proliferation, migration, and invasion through apoptosis regulation in the EZH2/FOXO1 pathway." (PMID 40191206, 2025). "FOXO1 is an essential regulator of endothelial cell proliferation and a tumor suppressor in different cancer types, including liver, endometrial adenocarcinoma, breast, and ovarian cancer." (PMID 38256218, 2024). "In ovarian cancer cells, it has been shown that Trx1 binds to the transcription factor forkhead box protein O1 (FOXO1) and induces its translocation to the nucleus, and thereby promotes the expression of FOXO1-dependent genes that protect the tumor from cell death." (PMID 39334737, 2024). "In addition, it has been found that enhancing nuclear FOXO1 improved the efficacy of cisplatin in reducing tumor volume in an ovarian cancer xenograft model." (PMID 37880374, 2023).